CDKN2A (cyclin dependent kinase inhibitor 2A)
Diseases named in the same sentence as CDKN2A in open-access papers (continued):
Sharing a sentence is not in itself a finding about the gene and the disease.
cancer (continued). "On the other hand, according to the catalog of somatic mutations in cancer (COSMIC), PC9 cells harbor mutations in the genes encoding such key regulators of cell cycle progression as CCND2 and CDKN2A." (PMID 32183160, 2020). "For instance, p16INK4a (CDKN2A) which acts as a cyclin-dependent kinase inhibitor essential for TSGs, can undergo hypermethylation in cancer." (PMID 31540128, 2019). "In total, 91 genes were upregulated while 21 showed lower levels of expression, 12 of them were cancer-related genes: two deleted (CDKN2A and PTPRD) and nine amplified (EGFR among others)." (PMID 31703248, 2019). "Hypermethylation of gene promoters in cancer causes downregulation of genes involved in cell-cycle regulation, including BRCA1, CDKN2A, RASSF1A, LOTI, DAPK, and ICAM-l." (PMID 30646939, 2019). "Especially, loss of functional tumor suppressor genes, including CDKN2A/B, PTEN, and RB1, is frequently observed across a broad range of cancer types, including GBM." (PMID 30898893, 2019). "Upregulation of CDKN2A (p16) in early cancer is an indication of the host’s response in deactivating pRb and releasing the E2F family." (PMID 31319555, 2019). "FadA is a key virulence factor of F. nucleatum and alters macrophage infiltration and methylation of the cyclin-dependent kinase inhibitor 2A (CDKN2A) promoter in cancer lesions." (PMID 30642137, 2019). "Using DNA copy number data from 9,744 human cancer specimens, we demonstrate that linear deletion limitation exists and exposes deletion-limiting genes for seven known deletion targets (CDKN2A, RB1, PTEN, MAP2K4, NF1, SMAD4, and LINC00290)." (PMID 31341961, 2019). "Our bioinformatics analysis via mining public pharmacogenomic datasets indicates that the IC50 value of palbociclib is positively correlated with the transcription level of the CDKN2A gene in 522 cancer cell lines." (PMID 31652270, 2019). "Inactivation of the CDKN2a locus is rare in thyroid follicular adenomas and carcinomas, where p14ARF protein levels are strongly increased." (PMID 30836703, 2019). "CCND1 amplification and overexpression as well as CDKN2A inactivation are frequent genetic alterations in many cancers, including NPC." (PMID 30236142, 2018). "Deletion of metabolic enzyme 5-methylthioadenosine phosphorylase (MTAP) is a frequently observed phenomenon in many cancers harboring CDKN2A (p16INK4a and p14ARF) tumor suppressor gene deletion." (PMID 30613353, 2018). "Data show that gene-silencing hyper-methylation in the promoter region of CDKN2A or overexpression of CCND1 frequently occurs in several cancer types." (PMID 29492214, 2018).
cancer (continued). "Several other upstream regulators appeared to play a role in cell growth, DNA replication, and cancer (CDKN2A, TCF3, PARP1, let-7a-5p)." (PMID 30327482, 2018). "The results showed that six cRMGs including OBSCN, CDKN2A, CSMD3, DMD, DNAH5, and KMT2Cwith MS or NS mutations have significant associations with prognosis in several cancer types." (PMID 30107644, 2018). "CDKN2A has a crucial function in cell cycle control and it is known to be inactivated in various types of cancer." (PMID 28403857, 2017). "Three pathways demonstrated top priorities, and the one with specific associations with cancers, ‘pathways in cancer,’ was analyzed with its four highlighted genes, namely, BIRC5, E2F1, CCNE1, and CDKN2A, which were validated using Oncomine." (PMID 28316892, 2017). "The association between CDKN2A/B deletion and the sensitivity to palbociclib, an FDA-approved CDK4/6 inhibitor, has been demonstrated in many cancers." (PMID 29089060, 2017). "CDKN2A inactivation has been correlated with poor prognosis independently of other traditional factors; in addition, CDKN2A alterations are discerned in more advanced, aggressive cancer." (PMID 28854942, 2017). "CDKN2A ranked in the top 0.1% of genes differentially expressed after MAX restoration in GIST48 and was the highest ranking cancer-associated gene." (PMID 28270683, 2017). "Related with this, the CDKN2B-AS1 and CDKN2A genes have not only been associated with POAG risk, but also with cancer and many other diseases that involve other tissues." (PMID 29104244, 2017). "The loss of CDKN2A and CDKN2B was observed in various cancers through deletion, inactivating mutations, epigenetic silencing or post-translational modification." (PMID 29156722, 2017). "The INK4a-ARF (CDKN2A) locus on chromosome 9p21 encodes two tumor suppressor proteins, p16 (INK4a) and p14 (ARF), whose functions are inactivated in many human cancers." (PMID 28545228, 2017). "The prevalence of aberrations in promoter methylation and their role in inactivation of CDKN2A have been investigated for various cancer types." (PMID 28403857, 2017). "Using this system, here we show simultaneous de novo DNA methylation of genes commonly methylated in cancer, CDKN2A, RASSF1, HIC1 and PTEN in primary breast cells isolated from healthy human breast tissue." (PMID 29133799, 2017). "Regardless of the tissue of origin, most HPV positive (HPV+) cancers show highly upregulated expression of the p16 product of the cyclin-dependent kinase inhibitor 2A (CDKN2A) gene." (PMID 29069809, 2017). "Recently, many epigenetic biomarkers have been studied in cancer diagnosis, including hMLH1, E-cadherin, CDKN2A, CDKN2B and APC in GC and SEPT9, SFRP2, THBD, SDC2, VIM and FBN1 in CRC." (PMID 29137404, 2017).
cancer (continued). "CDKN2A has length as the dominant determinant over amplitude in 6/8 cancers, while all 16 cancer types with MYC, CCND2, TERT, or AKT3 amplifications show low AUCs for both parameters." (PMID 26787600, 2016). "Genomic locus at chromosome 9p21 that contains the CDKN2A and CDKN2B tumor suppressor genes is inactivated through mutations, deletions and promoter methylation in multiple human cancers." (PMID 26909863, 2016). "The frequency of cancer specific homozygous deletion at CDKN2A is higher than at any other locus within human genome." (PMID 26909863, 2016). "H1975 cells expressed higher levels of CDKN2A (362.66 fold) and several other cancer drug resistance genes than A549 cells, but again most genes on the panel were more highly expressed in A549 cells than H1975 cells." (PMID 27765909, 2016). "We also investigated DNA methylation of the gene promoter of CDKN2A, at which DNA methylation is also seen in many cancers." (PMID 26911705, 2016). "Using AmBre, they discovered CDKN2A deletion breakpoints in six cancer cell lines, including MCF7, for which previous studies have failed to annotate the CDKN2A breakpoints, likely due to repetitive sequences." (PMID 26542840, 2015). "CDKN2A gene hypermethylation are common epigenetic aberrations in several type of cancer, including EC." (PMID 26283007, 2015). "The associations of the deletion of tumor suppressor genes CDKN2A, CDKN2B, and MTAP with the four significant enriched cancer types in this subgroup have been widely investigated and reported." (PMID 26148869, 2015). "CDKN2A (hypermethylated) is an inhibitor of CDK4 kinase and is a significant tumor suppressor gene, known to be mutated or deleted in different cancers." (PMID 26683690, 2015). "Subsequent studies found CDKN2A methylation in the plasma of 7/74 (9%), 3/33 (9%), and 4/50 (8%) of cancer-free controls, while methylation among patients with cancer included values of 25/110 (22%), 21/55 (38%), and 61% sensitivity." (PMID 25988180, 2015). "First, cancer genome sequencing has demonstrated disruption of this pathway through CDKN2A deletion, a potential biomarker of sensitivity to CDK4/6 inhibitors, in approximately 13–30 percent of Ewing sarcoma tumors." (PMID 26337082, 2015). "In cancers that have genomic driver insults in CDKN2A or CDKN2B, inhibition of CDK4/6 is likely to be a therapeutic option worth investigating." (PMID 26634163, 2015). "The first group of genes presented higher methylation levels in cancer tissues than in blood DNA (CDKN2A, APC, and DAPK1)." (PMID 26338139, 2015). "miR-24 directly targets CDKN1B and CDKN2A in keratinocytes and in different cancer-cell lines promoting their proliferation." (PMID 24605326, 2014). "Many genes in this region (e.g., the CDKN2A/CDKN2B locus and MTAP) were found to be associated with different types of cancer." (PMID 25522020, 2014). "Two cancers (#615 and #3008) had acquired homozygous deletions at the CDKN2A locus (chr9p21.3), and other homozygous deletions present in single cancers involved genes such as PPARGC1A, RFX3 and FAT1." (PMID 24777035, 2014). "One of the most relevant alterations is represented by the p16 (CDKN2A)-CCNDs/CDK-Rb pathway frequently altered in various types of cancers." (PMID 24605326, 2014).
cancer (continued). "The human CDKN2A gene was chosen in this analysis as an example of human endogenous genes potentially relevant for clinical use against cancer cells." (PMID 25170953, 2014). "When the results were statistically analyzed using paired-T test, RASSF1A, MGMT and CDKN2A showed comparable results in the cancer tissue and plasma samples." (PMID 24790823, 2014). "Although particular cancer-related genes such as CDKN2A and genes in the WNT signaling pathway were hypermethylated, epigenetic deregulation was not limited to cancer-associated genes but appeared to be a more widespread phenomenon." (PMID 24202323, 2013). "PcG genes are overexpressed in many cancers, and are considered oncogenic in part, by their repressing effect, notably on Cdkn2a [Sauvageau and Sauvageau, 2010]." (PMID 23192652, 2013). "This led to the discovery of two classes of focal deletions in human cancer, one that resembles deletions affecting common fragile sites and the other that resembles deletions affecting CDKN2A/B." (PMID 23805207, 2013). "Mutations/polymorphisms of many cancer susceptibility genes (such as BRCA1, CDKN2A, XPD, VDR, etc.)lead to tumour development." (PMID 23805825, 2013). "Six COPD patients developed cancer after five years from the initial COPD diagnosis at 2006–2007.We also evaluated the frequency of CDKN2A, CDH1 and MGMT promoter methylation in sputum samples of the groups under study." (PMID 22818553, 2012). "Of note are the changes in expressions of TBX (-2, -3) and CDKN2A occur in opposite directions in cancer." (PMID 22829758, 2012). "Collectively, regarding chromosomal aberrations at these two cancer-related loci, every examined carcinoma including the two cell lines contained either the Met amplification or the Cdkn2a/2b deletion." (PMID 22952676, 2012). "CDKN2a/INK4a located on 9p21 is frequently inactivated in oral epithelial pre-cancer and cancer via the following events: LOH, hypermethylation, deletion, mutation." (PMID 22376902, 2012). "The CDKN2A locus is deleted or silenced in many forms of cancer, including T- and preB cell leukemia." (PMID 22053823, 2011). "The predictive accuracy of RB1 status by the CCND1/CDKN2A ratio was examined with the original 30 cancer cell lines which were used to develop the RB1 gene signature as a training set." (PMID 21447152, 2011). "The instability of the CDKN2a/INK4 locus located on 9p21 is reported to be high in carcinoma and the major inactivation of the p16INK4A/p14ARF genes results from promoter methylation, homozygous deletion, loss of heterozygosity and intragenic mutation." (PMID 21447181, 2011). "Mapping CNAs has become an important starting point for discovering new cancer genes, and indeed led to the original identification of CDKN2A and SMAD4 as TSGs." (PMID 18535672, 2008). "In a series of proof-of-concept experiments, we were able to identify cancer-derived CDKN2A genomic breakpoints when more than 99.9% of wild type genome was present in a model system." (PMID 17440616, 2007). "This is even more true because some of the predisposing variants may carry a risk for other cancers or diseases later in life, examples being mutations in BRCA2, STK11, BLM, and CDKN2A, among other genes." (PMID 40340749, 2025).
cancer (continued). "However, CDKN2A is located on chromosome band 9p21, one of the most common genomic alteration regions in human cancers." (PMID 39925808, 2025). "Studies have shown that CDKN2A expression correlates with lymphocyte infiltration levels in 22 types of pan-cancers and may serve as a biomarker for immune infiltration in cancer." (PMID 40083663, 2025). "This implies that the expression regulatory mechanisms of the CDKN2A gene may differ among different types of cancers, and there may be a complex relationship between its expression changes and cancer progression stages." (PMID 40256740, 2025). "It has been well documented that CDKN2A involves in immune‐related activities in various cancers." (PMID 41310877, 2025). "Somatic alterations in CDKN2A are a frequent finding in many types of cancer." (PMID 38234851, 2025). "growth‐proliferation cell cycle‐associated genes such as Myc and Notch1,110 cancer‐associated genes such as Cdkn2a and Alpl, absence of TCR genes such as Trac and Trbc1/2 and elevated RPG expression, a distinct subset of precancerous T cells emerged." (PMID 40887856, 2025). "Additionally, a pan-cancer study has demonstrated that the total expression of CDKN2A was significantly elevated in LUAD." (PMID 41341386, 2025). "However, this particular observation was limited to patients diagnosed with six specific types of cancer and having CDKN2A-MUT." (PMID 38822443, 2024). "Patients with CDKN2A ALT had poor prognosis in as many as 12 primary cancer types." (PMID 38822443, 2024). "Among them, the tumor suppressor genes CDKN2A and RB1 are frequently inactivated by copy number deletions or point mutations, whereas the oncogenes CDK4, CDK2, CCND1, and CCNE1 are recurrently amplified in the genomes of some human cancers." (PMID 39351198, 2024). "By bridging computational innovation with clinical application, our work not only underscores the pivotal role of CDKN2A in cancer prognosis but also marks a step forward in the quest for personalized cancer therapies, aligning with the broader objectives of precision medicine." (PMID 38751024, 2024). "Moreover, MUC1-C’s role in cancer progression is further confirmed by enhancing the binding of BMI1 to the CDKN2A promoter and suppressing the expression of tumor suppressor genes like p16INK4a." (PMID 38361923, 2024). "Approximately 10% of all human cancers exhibit frequent deletions of both CDKN2A and MTAP." (PMID 39315676, 2024). "There hasn’t been any research on CDKN2A in all types of cancer, however." (PMID 38206516, 2024).